IL1B (interleukin 1 beta)
Diseases named in the same sentence as IL1B in open-access papers (continued):
Sharing a sentence is not in itself a finding about the gene and the disease.
atherosclerosis (continued). "The maturation and release of IL-1β are mainly regulated by the NLRP3 inflammasome, which plays an important role in many inflammatory diseases, such as atherosclerosis and autoimmune diseases." (PMID 33771213, 2021). "Up-regulation of miR-9 reduced aortic plaque area, the proliferation of collagen fibers, Mac-3-labeled macrophages and levels of IL-6, IL-1β, and TNF-α by suppressing SDC2 and the FAK/ERK signaling pathway, thereby ameliorating atherosclerosis in ACS mice." (PMID 32765295, 2020). "The cytokine IL-1β, which is downstream of the NLRP3 inflammasome, acts as an important mediator for the development of atherosclerosis and was quantified by ELISA." (PMID 31993073, 2020). "Previous studies in HFD-induced atherosclerosis mice reported that BBR administration remarkably reduced the mRNA expression of pro-inflammatory cytokines, including TNF-α, IL-1β, and IL-6, in ileal and carotid arteries." (PMID 32231564, 2020). "The severity of atherosclerosis correlates with inflammasome activity and NLRP3/caspase 1-mediated generation of IL-1β and IL-1α in human atherosclerotic plaque." (PMID 33172487, 2020). "In laboratory models, PAPP-A expression increases in damaged vessels and human plug atherosclerosis by stimulation of Tumor Necrosis Factor (TNF) and Interleukin-1 beta." (PMID 32500016, 2020). "Increased expression of this gene was observed in our study for NiCl2, as were other genes involved in inflammation such as IL1B and SERPINA (canonical pathways related to atherosclerosis and acute phase signaling)." (PMID 32244462, 2020). "It shows antioxidant properties against LDL-oxidation, thus potentially preventing atherosclerosis, and anti-inflammatory properties by decreasing the expression of TNF-α, interleukins IL-6 and IL-1b in a mouse macrophage cell line." (PMID 33237940, 2020). "Several inflammatory cytokines, such as interleukin-1β (IL-1β) and tumor necrosis factor-α (TNF-α), involved in the pro-inflammatory signaling in the atherosclerosis progression." (PMID 32472055, 2020). "In atherosclerosis, the NLRP3 inflammasome drives IL-1β release, thus contributing to the progression of atherosclerosis." (PMID 32148650, 2020). "Therefore, we examined whether a reactive dicarbonyl scavenger could block the pro-inflammatory cytokine response of peritoneal macrophages to ox-LDL, as reflected by reduced mRNA levels of IL1β and IL-6, which are relevant to the development of atherosclerosis." (PMID 32629758, 2020). "Here, we found that compared with the Control group mice, serum levels of TNF-α, IL-1β, IL-6 were significantly increased, and IL-10 and ADPN levels were significantly decreased in HFD-induced atherosclerosis mice (Model group; all p < 0.001)." (PMID 32231564, 2020). "Inflammation in atherosclerosis is orchestrated by cytokines and IFN-γ, IL-1β and TNF-α represent three major pro-atherogenic cytokines." (PMID 31202985, 2019). "In addition, exogenous leptin influences IL1B and TNFA gene expressions, which may moderate the inflammatory reaction progress in this examined adipose tissue, showing leptin as a significant risk factor in atherosclerosis progression." (PMID 31780867, 2019). "An overexpression of inflammatory cytokines/chemokines, such as IL-1β, -6, -8, and MCP-1, induces cell migration and adhesion, angiogenesis, and vascular permeability to exacerbate atherosclerosis." (PMID 31452653, 2019). "Its activation triggers inflammatory cytokines (such as MCP-1, IL-1β, and TNF-α) production and release, which results in inflammatory cascade and thereby promotes atherosclerosis." (PMID 30881312, 2019). "Among them, interleukin 1β (IL-1β), tumor necrosis factor α (TNF-α), IL-6, and monocyte chemokine protein 1 (MCP-1) are highly secreted and play major roles in atherosclerosis, VSMC dysfunctions, and inflammation of the arterial wall." (PMID 31824304, 2019).
atherosclerosis (continued). "We first observe that high-salt intake promotes atherosclerosis formation in the aortas of ApoE−/− mice, through inducing the expression of NFAT5, NLRP3, and IL-1β in endothelium." (PMID 31429763, 2019). "We demonstrate that CCTV target the IL-1β pathway upstream, while its high affinity to CCR2 allowed for atherosclerosis delivery and imaging." (PMID 31723548, 2019). "In the atherosclerosis + vector group, serum levels of TNF-α and IL-1β significantly increased (P < 0.01), whereas the serum level of TGF-β1 significantly decreased (P < 0.05), as compared with the control group." (PMID 31781638, 2019). "Disturbed balance in the action of IL1A, IL1B and IL1RA leads to the development and progression of atherosclerosis." (PMID 31480765, 2019). "The present study revealed that the secretion of inflammatory factors (TNF-α and IL-1β) and chemotactic factor (MCP-1) by macrophages was driven by NF-κB, contributing to more severe inflammatory and autoimmune reaction in atherosclerosis progression." (PMID 30314997, 2018). "The higher levels of cytokines in CAE, particularly IL-6, IL-8, IFN-γ, IL-1β, and TNF-α are similar to those in atherosclerosis, where TH1 enhances macrophage activation through IFN-γ and IL-2." (PMID 29337902, 2018). "Macrophages are a major driver of pathogenesis in atherosclerosis, by secreting inflammatory cytokines, such as TNF-α and interleukin-1β (IL-1β), and making communication with other immune cells, such as Th1 cells." (PMID 29760701, 2018). "For one thing, CHC can enhance vascular wall inflammatory responses and lead to atherosclerosis by active NLRP3 inflammasomes, which regulate caspase-1 activation and subsequent processing of pro-IL-1β, triggering IL-1 secretion." (PMID 29133791, 2017). "Several cytokines (e.g. IL1β, IL6, and TNFα) are known to stimulate the expression of ICAM-1 and VCAM-1, two important molecules involved in the development of atherosclerosis." (PMID 27277003, 2016). "Therefore, the action of IL-1α may suffice to allow cell migration and compensatory remodeling when targeting IL-1β to reduce inflammation in atherosclerosis, avoiding the potentially adverse effects of abrogation of signaling by both isoforms noted in IL-1R1-deficient mice." (PMID 27032103, 2016). "Herein, we have shown that MED can significantly inhibit the ox-LDL-induced expression of TNF-α, IL-6, and IL-1β both in RAW264.7 cells and in plaque lesion areas, which suggests that MED can suppress inflammatory responses in atherosclerosis." (PMID 26045945, 2015). "To further reveal the mechanisms of reducing atherosclerosis lesions by blocking TLR4/NF-κB, we investigated the effects of Ad-TLR4 siRNA and NF-κB antagonist PDTC on inflammatory cytokines such IL-1β, MCP-1, and TNF-α." (PMID 25860573, 2015). "In atherosclerosis and obesity, NOD-like receptor protein (NLRP)-3 inflammasome (the inflammasome that controls caspase-1 activity and thus IL-1β processing to its mature form) was a key driving factor in progression of the diseases." (PMID 25705177, 2015). "In that trial, no reduction of IL‐1β, IL‐6, or CRP was observed, suggesting that future trials should more specifically target pathways that are more tightly linked to atherosclerosis." (PMID 41489606, 2026). "Firstly, we demonstrated that RSV might inhibit ferroptosis to exert anti‐atherosclerosis effect; In addition, RSV regulates ferroptosis mainly through six biomarkers, including IL1B, RELA, HIF1A, SRC, PTEN, and MAPK1, in AS treatment." (PMID 40697701, 2025). "In mouse models of atherosclerosis, S1PR2 signaling in activated macrophages was shown to promote production of proinflammatory cytokines (e.g., IL-1β, IL-18), and S1PR2 may retain macrophages in atherosclerotic plaques." (PMID 39854311, 2025).
atherosclerosis (continued). "IL-1β plays a crucial role in atherogenesis as it promotes the expression of adhesion molecules and chemokines, including ICAM-1, VCAM-1, and MCP-1, which recruit leukocytes and mononuclear phagocytes during the early stages of atherosclerosis development." (PMID 40700116, 2025). "In addition, we found that IL-1β, even at 100 pg/mL in the presence of MCP-1, elicited pronounced effects on the early events in atherosclerosis." (PMID 41424804, 2025). "What's more, it was demonstrated that PLT can accelerate atherosclerosis formation by regulating the expression levels of cytokines like SOCS3 and IL-1β, inducing monocyte macrophages to produce inflammatory features, and promoting monocyte recruitment at plaques." (PMID 40980181, 2025). "In a study we included, it was shown that Sal B could exert anti-inflammatory activity by inhibiting the STAT3/NF-κB signalling pathway and suppressing the expression of the inflammatory factors IL-1β, IL-6, and TNF-α, thereby attenuating atherosclerosis." (PMID 40606622, 2025). "This research reveals that KMUP-1 co- and posttreatment could inhibit atherosclerotic plaque formation and atherosclerosis lesions by suppressing inflammation in HFD-fed mice (i.e., elevation of IL-1β and TNF-α)." (PMID 41194853, 2025). "In atherosclerosis, a decrease in the expression of FGFR1 receptors has been observed; it has been attributed to the action of pro-inflammatory mediators, including IFN-γ, TNF-α, and IL-1β." (PMID 41303445, 2025). "For flaxseed oil exhibited anti-atherosclerosis activity in high-fat diet-induced ApoE−/− mice, the acetic acid and propionic acid were negatively correlated with LPS, TNF-α, IL-1β, and IL-17A in plasma and with TNF-α, IL-1β, and IL-6 in the aorta." (PMID 39403395, 2024). "To extrapolate the translational relevance of our novel findings observed in mouse model system to human atherosclerosis, first, we found induction of TRIM13 and its downstream effectors in HASMCs and PMA-differentiated THP1 cells in response to proatherogenic cue, IL-1β." (PMID 38537695, 2024). "Increased expression of pro-inflammatory cytokines, such as IL-1β, could regulate the expression of cholesterol efflux protein ABCA1 in macrophages, thereby promoting foam cell formation and development of atherosclerosis." (PMID 39050859, 2024). "This study found that IL‐1β enhanced YAP‐mediated chemokine production in macrophages by activating TRAF6, highlighting a pivotal role of TRAF6 in the inflammation‐driven progression of atherosclerosis." (PMID 38778460, 2024). "NLRP3 deficiency reduced diet-induced atherosclerosis in female LDL-receptor deficient mice but not in males, a disease also highly dependent on leukocyte recruitment and IL-1β." (PMID 39654901, 2024). "In atherosclerosis and endothelial dysfunction, activation of LOX-1 stimulates the NF-κB signaling pathway to promote the expression of proinflammatory cytokines, such as IL-1b, TNF-α, MCP1, IL-8, and IL-6." (PMID 36982155, 2023). "The level of the pro-inflammatory factor IL-1β was significantly decreased and the levels of anti-inflammatory factors eNOS, TGFβ, Arg1, and IL-10 were significantly increased after GLSP treatment in early and advanced atherosclerosis." (PMID 36923537, 2023). "Interestingly, although the population was mainly beyond 70 years old and affected by advanced stage atherosclerosis, a significant difference was found regarding inflammatory markers, with increased levels of hs-CRP and IL-1β in T2DM patients." (PMID 37710315, 2023). "Intriguingly, two different research groups showed that inhibiting of IL-1β signaling in vascular wall rather than systemic inhibition is responsible for the beneficial effect on atherosclerosis burden reduction." (PMID 37539090, 2023).
atherosclerosis (continued). "As atherosclerosis is known to be induced by vascular inflammation, we studied the effect of GV1001 on vascular inflammation in WT mice by determining the expression levels of pro-inflammatory cytokines, such as IL-1β, TNF-α, and IL-6." (PMID 37628753, 2023). "Regarding the effect on cytokine production induced by BPA exposure in HUVECs, we witnessed a massive release of IL-8, IL-1β, and MCP-1, whose over-expression induces cell migration and adhesion, angiogenesis, and vascular permeability exacerbating atherosclerosis." (PMID 37112618, 2023). "Interestingly, basal circulating IL-1β and TNF-α are higher in men compared to women and their response is also higher in males in several diseases like atherosclerosis and vasculitis." (PMID 37810621, 2023). "The lack of MCP-1, MCP-1 receptor CCR2 inhibition, IL-1β deficiency, and TNF-α inhibition have been shown to decrease atherosclerosis formation." (PMID 37107335, 2023). "IL-1β knockdown significantly downregulated TNF-α, IL-6, and IL-8, which implied IL-1β cytokine could be a pharmacological target to prevent atherosclerosis induced by cigarette smoke." (PMID 36791122, 2023). "Indeed, atherosclerosis and CHD patients have live bacteria and significantly higher levels of IL-1β and other pro-inflammatory markers, which directly stimulates atheroma formation and can worsen periodontal destruction." (PMID 37974134, 2023). "IL-1β and IL-18, both by-products of NLRP3 inflammasome activation, appear to have a relevant contribution in the occurrence and propagation of atherosclerosis which is corroborated by abundant data obtained from the evaluation of atherosclerotic plaques in rodents and humans." (PMID 37175869, 2023). "Another study have shown that when the function of CMA is damaged during the progression of atherosclerosis, it can increase the activation of inflammatory body NLRP3 and the secretion of IL-1β, so as to promote the progress of vascular inflammation and atherosclerosis." (PMID 37063954, 2023). "We then analyzed the level of IL-1β, IL-18, TNF-α and NF-κB p65 in arteries of atherosclerosis." (PMID 36759876, 2023). "Finally, eight hub genes were identified, and IL-1β, VEGFA, and MMP9 genes in the fluid shear stress and atherosclerosis pathway are the most likely target genes in treating atherosclerosis." (PMID 37880698, 2023). "IL-1β is one of the well-known inflammatory effector molecules during period of NLRP3 inflammasome activation, and also plays a pro-atherogenic role in the progression of atherosclerosis." (PMID 36304814, 2022). "Literature reports have demonstrated that atherosclerosis is a chronic inflammatory disease, with the characteristic of inflammatory cell infiltration and secretion of various inflammatory factors, including TNF-α, IL-6, and IL-1β." (PMID 36176426, 2022). "The CANTOS trial, assessing monoclonal antibody inhibition of IL-1b, has clearly demonstrated a benefit of attenuating inflammation independent of cholesterol lowering therapies in atherosclerosis." (PMID 35634304, 2022). "Il-1β increases the expression of adhesion molecules and chemokines, such as ICAM-1, VCAM-1 and MCP-1, which recruit leukocytes and mononuclear phagocytes at the initial stages of atherosclerosis." (PMID 36497101, 2022). "Moreover, TP decreased the secretion of ox-LDL-induced tumor necrosis factor alpha (TNF-α), interleukin 1 beta (IL-1β), and monocyte chemotactic protein-1 (MCP-1), an important profoam cell cytokine in atherosclerosis." (PMID 36387364, 2022). "The dysfunction in psoriasis includes systemic inflammation involving cytokines, such as IL-17, TNF-α and IFN-γ, as well as inflammatory transcripts such as CXCL10, IL-1β and VCAM-1.Psoriasis increases vascular stiffness and atherosclerosis tthrough the IL-17 pathway." (PMID 36211578, 2022). "In addition, CCL4, TLR2, IL1B and PTPRC were considered to be immune marker genes in atherosclerosis development." (PMID 35509837, 2022).
atherosclerosis (continued). "IL-1β, a therapeutic target in atherosclerosis and other cardiovascular diseases, signals through JNK and NF-κB and inhibition of IL-1β may decrease the production of MMP3, SMC chemotaxis, and inflammasome-mediated inflammation." (PMID 36233314, 2022). "IL-1β was evidentially upregulated, while STAT3 was significantly downregulated in the atheroma plaque group, which indicated potential key roles for both in atherosclerosis progression." (PMID 36456628, 2022). "The use of canakinumab, an anti-IL-1β monoclonal antibody, in the context of atherosclerosis, has been promising, however, not enough data is available on its use in AD." (PMID 33800271, 2021). "A study has reported that fatty-acid-mediated mitochondrial uncoupling facilitates NLRP3-independent interleukin 1α (IL-1α) release in vitro, but not that of IL-1β, and atherosclerosis development in vivo." (PMID 33807807, 2021). "It is not of limited importance the impact of IL-1b in atherosclerosis, but likely this cytokine plays a major role in advanced clinical stages of atherosclerosis, such as angina, myocardial infarction, and cerebral stoke, as evident in literature." (PMID 34095164, 2021). "As several experimental and clinical reports have demonstrated that IL-1β is a proatherogenic cytokine, NLRP3 inflammasome activation could contribute to the progression of atherosclerosis." (PMID 33807807, 2021). "On the other hand, IL-1β neutralization during the late stages of atherosclerosis did not yield a significant reduction in disease manifestations in a mouse model." (PMID 33562334, 2021). "There is abundant evidence from animal studies showing that SGLT2 inhibitors slow down the progression of atherosclerosis and exert an anti-inflammatory effect by reducing the expression of proinflammatory cytokines, including TNF-α, IL-1β, IL-6, MCP-1, ICAM, VCAM." (PMID 34885795, 2021). "Their work showed that IL-1β antibody administration in late-stage atherosclerosis produced no changes in lesion size and in fact decreased beneficial outward remodeling." (PMID 33800271, 2021). "TNFα could induce IL6 and IL1β as a cellular signaling molecule attributing to the inflammatory regulation in atherosclerosis, or act as a pro-inflammatory molecule to promote hypertension or atherosclerosis with IL6 and IL1β." (PMID 33318871, 2021). "Macrophages take up oxidized LDL via scavenger receptors which, once inside the cell, induce cholesterol crystals that ultimately activate the inflammasome to release IL-1β and TNF cytokines, which are mediators of inflammation in both cancer and atherosclerosis 49-52." (PMID 34234868, 2021). "We found that VSMCs (Myh11+) undergoing transdifferentiation to macrophages-like cells in human atherosclerotic plaques co-express cleaved caspase 1 as well as IL-1β, indicating the involvement of NLRP3 inflammasome activation in VSMCs phenotypic switch in human atherosclerosis." (PMID 35008765, 2021). "Measurement of cytokines and proteases in the supernatants of HAoSMCs confirmed that inflammatory mediators, such as CXCL8, IL-6, IL-1β, and IL-1α and proteases, such as MMP-10 [role in atherosclerosis and vascular calcification], were produced and released by HAoSMCs upon aging in vitro." (PMID 34313809, 2021). "Though Nlrp3/AIM2 and IL-1β nexus is an emerging atherogenic pathway, the direct role of GsdmD in atherosclerosis is not yet fully clear." (PMID 34395445, 2021). "In a study of atherosclerosis, it was reported that AMPK was activated in blood cells and plaques, and serum IL-1β or TNFα was decreased in a urate-lowering mouse model fed HFD in which uric acid levels were decreased by the administration of allopurinol or overexpression of uricase." (PMID 34830282, 2021). "In contrast to Nlrp3 inflammasome and IL-1β, the direct role of GsdmD in atherosclerosis is not yet clear." (PMID 34395445, 2021).